PGR (progesterone receptor)
Diseases named in the same sentence as PGR in open-access papers (continued):
Sharing a sentence is not in itself a finding about the gene and the disease.
invasive carcinoma (23 papers, 2005 to 2025). A carcinoma that is not confined to the epithelium, and has spread to the surrounding stroma. "In 2017, a 61-year-old female patient presented with a Luminal B lobular-invasive carcinoma G2 of the breast (pT1c, pN1a (1/2 sn), M0, R0, L0, V0, Pn0), ER (estrogen receptor) 100%, PgR (progesterone receptor) 0%, HER2 0, Ki-67 10%." (PMID 40943419, 2025). "Histological examinations revealed a late relapse of the lobular-invasive carcinoma, ER 100%, PgR 0%, HER2 0, Ki-67 < 10%, Luminal B. The lead time from positive ctDNA to clinical relapse was consequently 4 years 8.9 months." (PMID 40943419, 2025). "In traditional invasive carcinoma, histological grade, lymph node status, estrogen receptor (ER), progesterone receptor (PR), and proliferation by Ki67 and HER2 are well-defined prognostic and predictive factors." (PMID 37296968, 2023). "The progesterone receptor expression was elevated in fibroadenomatous changes and in in situ carcinomas and decreased in invasive carcinomas." (PMID 33808541, 2021). "Despite the unquestionable contribution of ER and PgR testing for a better therapeutic implication, it appears necessary to examine the correlation between ER/PgR status with standard clinicopathologic parameters of primary invasive carcinomas in 302 patients." (PMID 28173783, 2017). "Estrogen receptor (ER) and progesterone receptor (PgR) expression are more frequent in lobular carcinomas than in other invasive carcinomas, although human epidermal growth factor receptor 2 (HER2) overexpression is rare." (PMID 25902937, 2015). "The invasive carcinoma was estrogen and progesterone receptor positive by immunohistochemistry." (PMID 16287501, 2005). "Immunohistochemistry showed positivity for estrogen receptor (ER) and progesterone receptor (PR) and equivocal human epidermal growth factor receptor 2 (HER-2) staining within the invasive carcinoma." (PMID 39099959, 2024). "The College of American Pathologists and the American Society of Clinical Oncology have recommended the evaluation of estrogen receptor (ER), progesterone receptor (PR), and HER2/neu receptor for all newly diagnosed cases of invasive carcinoma." (PMID 34912627, 2021). "On the right side, she presented with a T3, ER-positive and progesterone receptor–positive, HER2-negative, grade II invasive carcinoma NST with 20 of 23 involved lymph nodes." (PMID 32923864, 2019). "In keeping with diagnostic anatomo-pathological experience, the relative expression of ERBB2, ESR1, PGR and MKI67 in our study was often higher in DCIS samples than in samples enriched for invasive carcinomas." (PMID 30342538, 2018). "The results showed invasive carcinoma that was negative for estrogen receptor, progesterone receptor, and human epidermal growth factor receptor-2." (PMID 39377852, 2024). "The breast mass measured 3.2×1.8 cm, and histopathological examination revealed grade III invasive carcinoma of non-specific type, with ki-67 proliferation index of 70%, and estrogen receptor (ER), progesterone receptor (PR) and Her2/neu negative subtype." (PMID 36518309, 2022). "The term ‘pure apocrine carcinoma’ has been proposed to describe an invasive carcinoma with apocrine morphology that is oestrogen and progesterone receptor negative and androgen receptor positive." (PMID 34537861, 2022). "The invasive carcinoma was estrogen and progesterone receptor positive and negative for HER-2/neu protein overexpression by immunohistochemistry." (PMID 16287501, 2005). "A 50-year-old woman with a family history of Cowden syndrome was diagnosed with a T3N3 breast cancer, which was estrogen (ER) and progesterone receptor negative, human epidermal growth factor receptor 2 (HER2) negative, and was designated grade III invasive carcinoma of no special type (NST)." (PMID 32923864, 2019).
endometrioid carcinoma (22 papers, 2003 to 2026). "whereas loss of progesterone receptor (PR) expression is related to endometrioid carcinoma (especially PR-A)." (PMID 34322276, 2019). "Expression of OLFM4 was increased during endometrial carcinogenesis, linked to the differentiation of endometrioid adenocarcinoma, and positively related to the expression of oestrogen receptor-α (ERα) and progesterone receptor." (PMID 24495253, 2014). "Significantly higher levels of the PgR variable were observed among the patients with endometrioid adenocarcinoma than among those with serous adenocarcinoma (p = 0.029)." (PMID 38337838, 2024). "Specifically, low levels of progesterone receptor (PGR) expression are associated with a more aggressive disease course and worse outcomes in LGSOC and HGSOC, as well as in endometrioid carcinoma." (PMID 37569592, 2023). "Authors also observed that in most cases (except non-endometrioid carcinomas) PARP-1 expression positively correlated with progesterone receptor expression (p < 0.0001)." (PMID 36289716, 2022). "In this scenario, the panel of Progesterone receptor (PR) & vimentin (both positive in endometrioid carcinoma) with p16, Carcinoembryonic antigen (positive in endocervical carcinoma) is very helpful." (PMID 36200017, 2022). "The absence of squamous metaplasia, nuclear stratification, and ER/PgR expression may exclude the diagnosis of endometrioid carcinoma." (PMID 28841919, 2017). "After biopsy or surgery, immunohistochemistry is essential for confirming the diagnosis; investigating the presence of estrogen receptor, progesterone receptor, CK7, CK20, and caudal-related homeobox 2 can be used to differentiate colorectal cancer from endometrioid adenocarcinoma." (PMID 35965588, 2022). "On immunohistochemical analysis of the initial biopsy, the endometrioid carcinoma component was diffuse positive for ER and PgR, but negative for TTF-1 and GATA-3." (PMID 31174566, 2019). "On the other hand, if WT1 is negative, PgR expression suggests endometrioid carcinoma." (PMID 38573494, 2024).
adenomyosis (20 papers, 2009 to 2025). The growth of endometrial tissue inside the muscular wall of the uterine corpus. "Dienogest (DNG), a selective progesterone receptor agonist, effectively reduces adenomyosis-related pain but causes abnormal uterine bleeding (AUB) in some patients, likely due to pseudodecidual breakthrough bleeding, significantly impacting treatment compliance." (PMID 40662092, 2025). "The reduced expression of GATA2, which causes progesterone receptor expression in endometrial stromal cells of patients with adenomyosis, may be connected to the poor expression of LIF." (PMID 39886033, 2024). "One study employing sc-RNAseq reported an increase in PGR expression in adenomyosis lesions compared to the matched PP eutopic endometrium." (PMID 39935764, 2025). "Human studies were included and identified using a combination of exploded MeSH terms (‘adenomyosis’) and free-text search terms (‘oestrogen receptor’, ‘progesterone receptor’, ‘androgen receptor’, ‘hormone receptor’)." (PMID 39935764, 2025). "Women with adenomyosis often have reduced progesterone receptor (PR) expression in the myometrium, as well as dysfunction in progesterone signaling pathways." (PMID 40699697, 2025). "Conversely, membrane progesterone receptors (mPRs) or progesterone receptor membrane components (PGRMCs) are highly expressed in adenomyosis, indicating the complex regulation of progesterone in this disease." (PMID 41278208, 2025). "They found that progesterone receptor cells were significantly lower than the estrogen receptor cells in intrinsic adenomyosis (p < 0.05), but the expression levels of progesterone and estrogen receptors were found to be equivalent in the extrinsic subtype." (PMID 40708430, 2025). "Within the uteri of mice with adenomyosis, reduced expression of the progesterone receptor and a decreased expression of two implantation-related markers (HoxA10 and integrin β3) were observed." (PMID 38451875, 2024). "The progesterone receptor was lower expressed in the uteri of adenomyosis-induced mice compared to control mice (P = 0.0101)." (PMID 38451875, 2024). "To assess progesterone responsiveness in the uterus of adenomyosis-induced mice, we examined progesterone receptor expression in the eutopic endometrium of the two groups of mice by immunofluorescence." (PMID 38451875, 2024). "Gossypol is clinically used in China to treat adenomyosis and hysteromyoma because of its ability to inhibit estrogen and progesterone by competitively binding to the estrogen receptor and progesterone receptor." (PMID 19698176, 2009). "However, progesterone receptor expression declines in the endometrium of individuals with adenomyosis." (PMID 39886033, 2024). "The disrupted estrous cyclicity, the compromised ovarian follicle development, the reduced fertility and progeny, the decreased expression of endometrial progesterone receptor and receptivity-related genes collectively suggest a potential contribution to the subfertility observed in adenomyosis." (PMID 38451875, 2024). "Also, in preterm labor, as in adenomyosis, progesterone receptor activator hypermethylation and an increase in progesterone isoform A (reduced uterine responsiveness to progesterone) occur." (PMID 39200389, 2024). "This resistance is primarily due to decreased expression of the progesterone receptor PGR-B, which is mainly resulting from DNA methylation-mediated suppression of PGR-B in the stromal cells of the adenomyosis." (PMID 41278208, 2025). "In a study of mouse adenomyosis, EGCG emerged as a promising treatment strategy that suppressed myometrial infiltration, improved generalized hyperalgesia, and reduced uterine contractility, while elevating the expression of the progesterone receptor." (PMID 39595579, 2024).
adenomyosis (continued). "According to Francesca Conway (2018), ulipristal acetate, also known as a selective progesterone receptor modulator (SPRM), exacerbated ultrasound features and painful symptoms in adenomyosis, even though it dramatically decreased CA-125 concentration in serum." (PMID 38543097, 2024).
lobular carcinoma (16 papers, 2002 to 2026). "Invasive lobular carcinomas also express the progesterone receptor (PR) at high rates (50%-70%), and less than 10% of these cells express HER2/ERBB2 (epidermal growth factor receptor 2)." (PMID 38665752, 2024). "Metastases from a lobular carcinoma of the breast were based on negativity for Estrogen and Progesteron receptors (ER, PgR) and also negativity for mammaglobin, endothelial transcription factor 3 (GATA 3), and gross cystic disease fluid protein 15 (GCDFP-15)." (PMID 31205468, 2019). "Histopathology confirmed mixed invasive ductal and lobular carcinoma that was estrogen receptor positive, progesterone receptor positive, and human epidermal growth factor receptor 2 negative." (PMID 30338173, 2018). "Pathology revealed a pT2N3M0 lobular carcinoma, with positive estrogen receptor (ER, 70%) and progesterone receptor (PR, 80%) immunostainings, proliferative index (Ki67/MIB-1) as high as 15%, and negative HER2/neu status." (PMID 24716084, 2014). "Histology and immunohistochemical profiling, with estrogen receptor (ER), progesterone receptor (PR), E-cadherin, GATA3, Mammaglobin, and GCDFP-15, favored the diagnosis of lobular breast carcinoma metastasis over primary gastric adenocarcinoma." (PMID 41743390, 2026). "Patient B was diagnosed with a screening-detected lobular carcinoma of the left breast, G2, ER 20%, PgR 10%, HER2 negative and Ki67 10%." (PMID 34068368, 2021). "The malignant cells were positive for p120 (cytoplasmic) and GATA3 and negative for estrogen receptor, progesterone receptor, human epidermal growth factor receptor 2, E-cadherin, gross cystic disease fluid protein 15 and mammaglobin, which indicated a lobular carcinoma phenotype of the breast." (PMID 28693516, 2017).
colorectal cancer (15 papers, 2011 to 2025). A primary or metastatic malignant neoplasm that affects the colon or rectum. "Few candidate-gene studies have evaluated variation in hormone receptors (ESR1, ESR2, PGR) in relation to colorectal cancer risk." (PMID 21627810, 2011). "first analyzed the progesterone levels of 77 patients with CRC, and immunohistochemistry was conducted to identify the overexpression of progesterone receptor in colorectal cancer." (PMID 38115900, 2023). "Although estrogen (ERα/ERβ), progesterone (PGR), and androgen (AR) receptors are pathologically altered in colorectal cancer (CRC), their simultaneous expression within the same cohort of patients was not previously measured." (PMID 37206439, 2023). "The present study was performed to investigate the factors related to the expression level of estrogen and progesterone receptor in patients with colorectal cancer." (PMID 34691180, 2021). "We observed little support for an association of gene variants in hormone receptors (ESR1, ESR2, PGR) and active estrogen synthesizers (HSD17B1, HSD17B2, and HSD17B4) with colorectal cancer risk among postmenopausal women of European descent." (PMID 21627810, 2011). "Specifically, triptonide exhibited a binding energy of -9.62 kcal/mol with PGR, a core target of hypertensive retinopathy, while methyl ursolate showed a binding energy of -9.71 kcal/mol with NFE2L2, a core target of colorectal cancer." (PMID 41938594, 2025). "The expression levels of PGR and ABCC3 were significantly different between the colorectal cancer stages." (PMID 36843944, 2023).
melanoma (15 papers, 2013 to 2025). A malignant, usually aggressive tumor composed of atypical, neoplastic melanocytes. "In cancer, DDX21 associated with the progesterone receptor and modulated leflunomide-induced nucleotide stress in melanoma cells." (PMID 39866844, 2025). "All but ESR1, PAX8, PGR, TMEFF2, were associated with prognosis of breast, cervical, colorectal, head and neck, liver, lung, melanoma, ovarian, pancreatic, renal, or urothelial cancers." (PMID 34680205, 2021). "On the other hand, the expression/activity of the progesterone receptor and the possible cross-reaction of apigenin with this receptor in melanoma cells still need to be clarified." (PMID 27833586, 2016). "Several retrospective reviews showed a worsened prognosis in pregnant women with melanoma and found that PgR and ER can be detected in melanoma tissue." (PMID 23510193, 2013). "However, it might be argued that while the complex network engaged by steroid receptors (AR, ER alpha or beta, PgR and others) has been deeply investigated in sex-hormone responsive malignancies, it remains still pending in melanoma." (PMID 39837817, 2025). "Since her primary CM showed no PgR expression, a direct mitogenic role of Pg on melanoma cells seems less probable, although we cannot rule out that the metastases could have expressed PgR, since we could not address this point due to scarce material from the liver biopsy." (PMID 23510193, 2013). "All other markers tested were negative (pan-melanoma, HMB45, Melan A, keratin AE1/AE3, desmin, alpha smooth muscle actin, h-caldesmon, CD34, p16, CD117, DOG1, myogenin, CD10, estrogen receptor (ER), progesterone receptor (PR), PAX8, WT1, synaptophysin, chromogranin A, CD99 and PRAME))." (PMID 39196362, 2024).
lung carcinoma (14 papers, 2010 to 2025). "These nuclear receptors actively regulate various cellular functions; in addition, the expression levels of many nuclear receptors, such as progesterone receptor (PR), have been identified as prognostic factors for lung cancer patients." (PMID 39311119, 2024). "PgR expression in lung cancer is lower than in benign tissues; however, the combination of estrogen and progestin increases tumor VEGF secretion in vitro." (PMID 37509283, 2023). "Estrogen, progesterone and reproductive hormones are thought to be involved in the development of lung cancer due to sex differences in the protein expression of estrogen receptor (ER)-α, ER-β, and progesterone receptor (PR) in lung cancer." (PMID 34112140, 2021). "Conversely, Di Nunno and colleagues didn't discover immunohistochemical reactivity of PgR in 248 lung cancer samples." (PMID 27690341, 2016). "Controlling the effects of the fitted independent variables, negative estrogen and progesterone receptor status (HR = 1.38; 95% CI: 1.21–1.57) was a strong downstream factor related to increased lung cancer attributed mortality." (PMID 33718108, 2020).
ductal carcinoma in situ (12 papers, 2002 to 2025). "The excised mass had a positive margin and was identified as ductal carcinoma in situ based on histopathological findings: Estrogen receptor (ER) (+), Progesterone receptor (PR) (+), HER2 (1+), and Ki67 (10%)." (PMID 34174941, 2021). "The histological findings were TisN0M0, ductal carcinoma in situ (DCIS), and immunostaining was ER positive, PgR positive, and HER2 positive." (PMID 39758290, 2025).
gastric cancer (12 papers, 2007 to 2024). A primary or metastatic malignant neoplasm involving the stomach. "The objective of the study was to investigate the role of genes (HSD3B1, CYP17A1, CYP19A1, HSD17B2, HSD17B1) involved in the steroid hormone biosynthesis pathway and progesterone receptor (PGR) in the etiology of gastric cancer in a population-based two-phase genetic association study." (PMID 23110082, 2012). "Therefore, polymorphic variants of PGR may be involved in modification of gastric cancer susceptibility by altering its encoded receptor status expression and function." (PMID 23110082, 2012). "Taking all these data into consideration, starting MHT to gastric cancer survivors should rather be avoided, and especially so in case of estrogen or progesterone receptor positive tumours." (PMID 30617760, 2020). "Altered estrogen and / or progesterone receptor expression has been documented for example in thyroid cancer, Hodgkin’s lymphoma, B-cell malignancies, brain tumours, prolactinoma, melanoma, lung cancer, colorectal cancer, gastric cancer and liver cancer." (PMID 30617760, 2020). "Additionally, the roles of progesterone receptor (PR) and androgen receptor (AR) in gastric cancer are poorly defined." (PMID 23199240, 2012). "In contrast, all PGR SNPs were not statistically significantly associated with gastric cancer risk." (PMID 23110082, 2012). "In MOC, Estrogen Receptor (ER) and Progesterone Receptor (PR) are usually not expressed, and the expression in gastric cancer is related to the degree of cell differentiation and histological type." (PMID 39040449, 2024). "PG I and PGR levels were found to be significantly lower in patients with CAG and gastric cancer (GC) compared to normal (p < 0.01), and the levels of PG I, PGR, and G-17 are strongly correlated with the grading of CAG and the location of lesions." (PMID 35665336, 2022).